AQP4 (aquaporin 4)
Diseases named in the same sentence as AQP4 in open-access papers (continued):
Sharing a sentence is not in itself a finding about the gene and the disease.
glioma (continued). "A strong correlation between peritumoral brain edema and upregulated astrocyte AQP4 expression in human gliomas suggests that increased AQP4 expression may be essential to the pathogenesis of peritumoral brain edema." (PMID 34631582, 2021). "Moreover, reports have shown that AQP4 is upregulated in glioma, which indirectly indicates poor CSF outflow in glioma." (PMID 35083148, 2021). "In sum, the expression and localization of AQP4 at the leading edges of migrating glioma cells support the idea that AQP4, similar to AQP1, could be a target of interest for novel drug-based GBM treatments." (PMID 34769339, 2021). "If the mechanisms of redistribution of AQP4 and Kir4.1 differ in low- and high-grade gliomas, this may suggest that the mechanisms of clustering of AQP4 and Kir4.1 at the glial endfeet membrane domains are also different." (PMID 33297299, 2020). "In addition, AQP4 was dramatically upregulated in glioma cell lines U251 and A172 than normal cell line NHA." (PMID 33817241, 2020). "For the first time, we demonstrated that the IDO1/TDO–Kyn–AhR signaling pathway could regulate AQP4, which is involved in the migration and invasion of glioma cells." (PMID 32296044, 2020). "Downregulation of AQP4 expression in glioma by pentamidine and temozolomide promoted apoptosis and inhibited cell migration, which could be a potential treatment for glioma." (PMID 32679804, 2020). "In consideration of the regulatory effect of LINC00461/miR-216a axis on AQP4 expression, we wondered whether different expression of AQP4 could affect its role in glioma cells." (PMID 33817241, 2020). "In this regard, it is likely that AQP4ex may be involved in brain tumors where mislocalization of AQP4 has been found, such as in glioma." (PMID 30935410, 2019). "In addition, experiments performed on a culture of normal astrocytes and glioma cells showed a potential effect of T3 on the expression of AQP4." (PMID 31019448, 2019). "In glioma cells AQP4 colocalizes with the chloride channel (ClC2) and the potassium-chloride co-transporter 1 (KCC1), which could provide a driving force for water efflux leading to cell shrinkage, augmenting invasiveness." (PMID 31477744, 2019). "AQP4 expression levels could correlate to the tumor grade, as AQP4 expression levels increase with higher glioma grades." (PMID 28423683, 2017). "More importantly, the redistribution of AQP4 and OAPs could be one of the earliest indicators of glioma transformation." (PMID 28423683, 2017). "It is assumed that AQP4 expression levels could correlate to the tumor grade, with the generally accepted viewpoint that AQP4 expression increases with higher glioma grades." (PMID 28423683, 2017). "AQP4, which is the water channel with by far the highest water flux capacity in the brain, has been found to be strongly up-regulated and redistributed across the entire surface of all glial tumor cells." (PMID 28423683, 2017). "All these data suggest the involvement of AQP4 in malignant brain tumors and indicated that AQP4 could serve as a potential target for therapy of glioma." (PMID 28423683, 2017). "Furthermore, the important roles of AQP4 in preventing drug resistance during glioma chemotherapy and of potential novel pharmacological blockers of AQP4 have been elucidated." (PMID 28423683, 2017). "Discoveries of the role of AQP4 in cell migration suggest that AQP4 could be a significant factor regarding glioma malignancies." (PMID 28423683, 2017). "Recently, accumulated evidence has pointed to AQP4 as a key molecule that could play a critical role in glioma development." (PMID 28423683, 2017). "We next investigated the effect of inhibiting the expression of AQP4 on glioma cell apoptosis." (PMID 23950863, 2013).
glioma (continued). "RG-2 glioma cells if grafted into the brain developed AQP4 expression." (PMID 22590566, 2012). "Accordingly, reintroduction of AQP4 into AQP4-deficient glioma cell lines enhanced cell adhesion rather than cell growth, whereas AQP1 expression led to enhanced cell growth and migration." (PMID 22590566, 2012). "The high expression level of AQP4 has been reported in glioma." (PMID 22808259, 2012). "In addition, high AQP4 expression levels are also detectable in well-differentiated low-grade gliomas and there is indication that only the expression of AQP1 enhanced cell growth and migration of gliomas, while AQP4 expression enhanced cell adhesion." (PMID 21548930, 2011). "However, another study reported the level of AQP-4 in glioma to be significantly decreased." (PMID 40464180, 2025). "To explore whether dynamic AQP4 regulation during the cell cycle is the potential molecule connecting MRI-kio with proliferation activity, we also stained AQP4 in human glioma biopsy sample and found that samples with higher Ki67 expression exhibited more pronounced AQP4 expression." (PMID 40225573, 2025). "Furthermore, the specific biological mechanisms by which AQP4 influences glioma prognosis are still unknown, and its functional role within apCAFs requires further exploration." (PMID 40788933, 2025). "Thus, AQP4 is a potential target for early glioma detection using targeted MRI." (PMID 38954698, 2024). "Thus, more effeorts should be directed towards investigating whether AQP4 redistribution impacts MMP-9-related malignancy in glioma patients." (PMID 39247976, 2024). "Moreover, our knowledge about AQP4 expression in glioma cells is currently limited." (PMID 39200356, 2024). "Finding particular AQP4 inhibitors may help develop new mechanism-based treatments for glioma." (PMID 39247976, 2024). "However, the complete understanding of the biological processes and curative importance of AQP4 in glioma remains unclear." (PMID 39247976, 2024). "Thus, we assume the alteration of AQP4 expression levels may involve the interaction between the immune microenvironment and tumor cell states, impacting glioma’s malignancy by transitioning into MES-like states." (PMID 36599974, 2023). "Interestingly, the AQP4 expression profile varies across glioma samples." (PMID 36599974, 2023). "In-depth molecular studies of AQP4 in GBM suggest that the state of AQP4 aggregation into AQP4 orthogonal arrays of particles (AQP4-OAPs) and disintegration of AQP4 into tetramers may be involved in determining the fate of glioma cells." (PMID 35910247, 2022). "Furthermore, more work should be done to find factors determining AQP4 protein relocalization and AQP4 aggregation state in the near future, and this would accelerate definitive evaluation of the role of AQP4 in the treatment of glioma and various other neurological diseases." (PMID 36523816, 2022). "The authors found that AQP4 protein aggregation/disaggregation into OAP influences the biology of glioma cells, demonstrating that AQP4 protein disaggregation may potentiate invasiveness potential, whereas AQP4 protein aggregation may activate the apoptotic path." (PMID 36523816, 2022). "Therefore, the present study aimed to explore the role of AQP4 in the immune regulation of glioma." (PMID 36523816, 2022). "Up-regulations of AQP1 and AQP4 could enhance migration and invasion of glioma cells." (PMID 34712604, 2021). "In addition, we used Evans Blue ex vivo to evaluate the contribution of AQP4-mediated fluid flux to the movement of subarachnoid CSF into and through the brain parenchyma and AQP4 expression on the endfeet of astrocytes around the vessels in glioma using immunofluorescence." (PMID 35083148, 2021). "Using AQP4 as a medium may restore the glymphatic system of the glioma and improve drug delivery." (PMID 35083148, 2021). "LINC00461/miR-216a/AQP4 pathway could contribute to tumorigenesis of glioma." (PMID 33817241, 2020).
glioma (continued). "AQP4-facilitated glioma invasion is dependent on co-expression of chloride channels (ClC2) and the potassium-chloride co-transporter 1 (KCC1) in invadopodia, which could provide the ionic driving force for water efflux leading to cell shrinkage that could augment invasiveness through ECM." (PMID 29922644, 2018). "Therefore, AQP4 could be regarded as a protective factor for the reduction of cerebral fluid accumulation in human gliomas, and a correlation between the degree of peritumoral edema and the expression level of AQP4 in peritumor could exist." (PMID 28423683, 2017). "Although the observations summarized in this review should be confirmed with more studies, we believe that they could provide critical information for the design of more focused research that will allow for systematic and definitive evaluation of the role of AQP4 in glioma treatments." (PMID 28423683, 2017). "Thus, specific up-regulation of the M1 isoform in glioma might explain the interesting phenomenon regarding up-regulated AQP4 in conjunction with down-regulated OAPs." (PMID 28423683, 2017). "In the rat glioma model, we also found the positive linear correlation between the ROI-averaged AQP4+ and Ki67+ fractions (r = 0.73, p < 0.0001)." (PMID 40225573, 2025). "Among the glioma subtypes, AQP1 and AQP4 are overexpressed in astrocytoma (LGG) and classical glioma (GBM)." (PMID 38476871, 2024). "GBM RNA transcriptome datasets were used to examine the expression levels of GFAP, AQP4, and PLEC in healthy tissue versus glioma; samples were obtained from 28 healthy human controls (HCs), 148 patients with astrocytoma, and 221 patients with GBM." (PMID 38263015, 2024). "Conducting an extensive search using PubMed on glioma/brain-cancer-related articles of ABCC8, ABCC9, KCNJ11, KCNJ8, AQP4, and KCNMA1 genes has yielded interesting results." (PMID 39200356, 2024). "AQP4, an orthodox AQP type, is upregulated in gliomas and is involved in the tumorigenesis process, that is, cell migration, invasion, and functional changes in the surrounding tissue." (PMID 38476871, 2024). "Our earlier research has shown that AQP4 has a major impact on the prognosis of GBM patients and the effectiveness of anti-glioma drug treatment." (PMID 39247976, 2024). "Peritumoral edema formation surrounding gliomas is considered to be driven by three main mechanisms: (i) increased BBB permeability, (ii) tumor angiogenesis, and (iii) increased aquaporin 4 expression." (PMID 37893105, 2023). "AQP4, the main subtype shown to contribute to BBB remodeling and brain edema in glioma, is discussed in further detail below." (PMID 36768856, 2023). "The role of AQP4 isoforms in GBM biology has been addressed in earlier studies, which have shown that high-grade gliomas display higher expression of AQP4 than low-grade tumors." (PMID 36523816, 2022). "For example, AQP4 expression was shown to be increased in glioblastoma multiforme (GBM), which is often accompanied by AQP4 redistribution in glioma cells." (PMID 35847914, 2022). "Two members of this family, AQP1 and AQP4, a have a consensus phosphorylation site for PKC, which is a known regulator of glioma cell invasion." (PMID 35847914, 2022). "Therefore, AQP4 EV-mediated transfer could be a tumour-supporting mechanism by which glioma cells can export their tumour-enhancing- phenotype or can promote a phenotypic switch either between the tumour and less malignant tumour cells or among tumour cells and stroma." (PMID 36071478, 2022). "Our immunofluorescence data show increased AQP4 staining of GBM infiltrated brain parenchyma, in which glioma cells reside." (PMID 35187599, 2022). "Previous studies have shown that p38 MAPK is involved in regulating AQP4 in different CNS disease models, such as ischemic, intracerebral hemorrhage (ICH), traumatic brain injury, epilepsy, glioma, and carbon monoxide (CO) poisoning." (PMID 35991296, 2022).
glioma (continued). "AQP1, AQP4 and AQP9 were reported to be related to angiogenesis, invasion and peritumoral edema in gliomas." (PMID 34712604, 2021). "And AQP subtypes, including AQP1, AQP4 and AQP9, are overexpressed in glioma cells and correlated with tumor grade and malignancy." (PMID 34712604, 2021). "The genes AQP4, BCAN, GFAP, PLP1, and S100B are part of the astrocytic, oligodendrocytic, or proneural glioma signatures." (PMID 34101353, 2021). "In glioma, IDO1/TDO was shown to account for Kyn release and subsequent AhR-activation mediated cell motility via the expression of aquaporin 4 (AQP4)." (PMID 33451095, 2021). "We also observed an interesting phenomenon: GFAP and AQP4 expression in the internal core and periphery of glioma differed, where the peripheral area was significantly enriched with GFAP and AQP4." (PMID 35083148, 2021). "In malignant glioma cells, OLIG2/DLL3 and AQP4/CLU distinguish tumor cells exhibiting transcriptomic features of oligodendrocytes and astrocytes, respectively." (PMID 34692159, 2020). "The expression of IDO1/TDO was positively correlated with the expression of aquaporin 4 (AQP4), implying the potential involvement of IDO1/TDO in glioma cell motility." (PMID 32296044, 2020). "Aquaporin-4 (AQP4), the main water channel of the brain, is highly expressed in animal glioma and human glioblastoma in situ." (PMID 22590566, 2012). "These non-canonical roles of AQP4 have generated increasing interest in its contribution to neuropathological states, particularly brain tumors of glial origin, including gliomas and astrocytomas." (PMID 41324079, 2025). "Existing evidence only mentions the increased expression of AQP4 in glioma-reactive astrocytes but does not further clarify its specific mechanisms in regulating the flow of edema fluid in gliomas." (PMID 40243478, 2025). "Although the transmembrane water-efflux rate measured via MRI can serve as a biomarker for AQP4 in gliomas, exogenous contrast agents targeting AQP4 have not been reported." (PMID 38954698, 2024). "Our results are supported by these findings, as aquaporin expression patterns increased when compared between molecular subtypes of gliomas: AQP1 is increased in other subtypes of LGG classification (astrocytoma); in contrast, AQP4 is increased in only the classical subtype GBM." (PMID 38476871, 2024). "Intriguingly, previous findings have suggested differential expression patterns of MMP-9 and AQP4 in different grades of gliomas, and co-analysis of MMP-9 and AQP4 may help to identify tumour type and their progression stages." (PMID 39247976, 2024). "The results demonstrated that, upon treatment with zoledronic acid, a remarkable change in cell morphology was specifically observed in glioma cells expressing AQP4-OAPs, whereas no such effect was observed in glioma cells expressing AQP4-tetramers." (PMID 39200356, 2024). "Numerous AQP4 modulators have been shown to have a significant inhibiting impact and potential therapeutic value for glioma; nonetheless, no one has received approval for usage in humans." (PMID 39247976, 2024). "To investigate whether this was the case in our settings, we stained for astrocyte end-feet and endothelial cells using anti-aquaporin 4 (AQP4) and anti-CD31 antibodies, respectively, along with STEM121 or HuNu to visualize the human glioma cells." (PMID 38195678, 2024). "Owing to the role of molecular markers in the early diagnosis of gliomas, we hypothesized that AQP1 and AQP4, as homeostatic brain proteins, could act as potential anticancer therapeutic targets." (PMID 38476871, 2024). "To demonstrate the meaning of AQP4 expression diversity, we used the TCGA GBM (the glioblastoma dataset, n = 163), LGG (the lower grade glioma dataset, n = 518), and GTEx normal brain tissues data (n = 207) to compare with all types of tumor samples and paired normal tissues." (PMID 36599974, 2023).
glioma (continued). "Furthermore, AQP4 plays a key role in the blood-brain barrier destruction in glioma, whereas AQP5 is closely related to glioma-related brain edema." (PMID 37280594, 2023). "Using D54MG glioma cells stably transfected with either AQP1 or AQP4 expression construct, it was further demonstrated that PKC activity regulates water permeability through phosphorylation of AQP4." (PMID 35847914, 2022). "Although a more detailed analysis is necessary, our results suggest that glioma cells in tumor tissue are likely not to express high levels of AQP4." (PMID 35187599, 2022). "In our previous study, we have also confirmed that AQP4 was highly expressed in GBM tissues and that AQP4 could impact glioma patients’ overall survival." (PMID 36523816, 2022). "In support of this conclusion, it should be considered that AQP4-OAPs are not compatible with migration of glioma cells and their survival." (PMID 35187599, 2022). "Using glioma cell lines, we have recently demonstrated that AQP4 tetramer expression potentiates glioma cell invasiveness ability while AQP4-OAP expression drives glioma cells towards the apoptotic path, indicating a key role for AQP4 aggregation state in glioma cell biology." (PMID 36071478, 2022). "In this report, using glioma cells stably transfected with either AQP1 or AQP4, it was clearly demonstrated that PKC activity regulates water permeability and that this phenomenon can be modulated by phosphorylation of AQP4." (PMID 35847914, 2022). "Expression and transfection studies of AQPs in several commonly used human glioma cell lines suggested that AQP4 enhanced cell adhesion, which was abolished without AQP1." (PMID 35847914, 2022). "Knockdown of LINC00461 suppressed glioma cell proliferation, migration, invasion, and TMZ resistance in U251 and A172 cells in vitro and inhibited tumor growth in vivo through targeting miR-216a and downregulating AQP4." (PMID 33817241, 2020). "Significant downregulation of water permeability of AQP4 after treatment with PKC activators was found in several different models, including in vivo rat models, oocytes expressing rAQP4, and human glioma cells." (PMID 32111087, 2020). "In vitro, cultured glioma cells did not express AQP4, whereas healthy astrocytes revealed a slight upregulation of both isoforms and only a few OAPs in freeze fracture analysis." (PMID 27483250, 2016). "Besides alteration in AQP4 expression, the water channel AQP1 is upregulated under pathological conditions, e.g. in glioma cells and reactive astrocytes as well as in reactive brain endothelial cells." (PMID 26115524, 2015). "Six out of the 17 interactions have been previously linked to invasion, migration or adhesion (EPHA4-Efnb3, SEMA5A-Plxnb3, AQP4-Dag1, FGFR1-Ncam1, FGF2-Sdc2, and APP-Aplp2) whereas only 3 interactions have been previously reported in glioma (SEMA5A-Plxnb3, AQP4-Dag1, and FGF2-Sdc2)." (PMID 25365423, 2014). "In this study, we showed for the first time implanted AQP4 negative glioma cells in animal brain or flank to express AQP4 specifically in the intracerebral gliomas but neither in the extracranial nor in the flank gliomas." (PMID 22590566, 2012). "This difference between the in vivo and in vitro situation led us to the idea to implant different AQP4 negative glioma cells into the brain." (PMID 22590566, 2012). "Cultured SMA cells did not stain for AQP4 but when implanted into mouse brains, SMA gliomas became immunoreactive for AQP4 (data not shown)." (PMID 22590566, 2012). "AQP4 staining in vivo normally is polarized in the astrocytic endfoot membranes at the glia limitans superficialis and perivascularis, but in C6 and RG2 tumors the AQP4 staining is redistributed over the whole glioma cell as in human glioblastoma." (PMID 22590566, 2012). "Most primary cells from glioblastoma tissue as well as glioma cell lines do not express AQP4 under culture conditions." (PMID 22590566, 2012).